CASP1 (caspase 1)
Diseases named in the same sentence as CASP1 in open-access papers (continued):
Sharing a sentence is not in itself a finding about the gene and the disease.
epilepsy (21 papers, 2018 to 2026). A brain disorder characterized by episodes of abnormally increased neuronal discharge resulting in transient episodes of sensory or motor neurological dysfunction, or psychic dysfunction. "Niche themes in the upper left quadrant, characterized by low centrality and high density, are highly developed and isolated or specialized themes, such as ‘caspase-1’, ‘epilepsy’, ‘acral melanoma’, ‘ace2’ and ‘crc’." (PMID 39927119, 2024). "Evidence for inhibition of caspase-1 has also been reported to show beneficial outcomes in animal models of epilepsy." (PMID 39014496, 2024). "Inhibiting the IL-1β converting enzyme (ICE)/caspase-1 is also being investigated as a possible target for managing drug-resistant epilepsies." (PMID 38078329, 2023). "Recently, the NLRP3 inflammasome, a key constituent of the inflammasome complex, has been implicated in the sterile inflammatory response via the processing of caspase-1, IL-18, and IL-1β in the setting of epilepsy and some other neurological diseases." (PMID 32005256, 2020). "Induction of caspase-1 and activation of IL-1β both occur in human epilepsy, and contribute to experimentally induced acute seizures." (PMID 32907600, 2020). "Alterations in proteolytic cleavage of pro-caspase 1 and 3 have already been described in different experimental epilepsy models." (PMID 33154418, 2020). "The development of caspase-1 inhibitor was largely attributed to the researches in epilepsy and HIV infection." (PMID 29440460, 2018). "VX-765 is an orally active caspase-1 inhibitor, which is well-tolerated in a 6 weeks long-phase II trial in patients with epilepsy." (PMID 29440460, 2018). "Furthermore, another caspase-1–specific inhibitor, belnacasan (VX-765), completed a phase II trial in patients with epilepsy showing safety and tolerability." (PMID 41436137, 2025). "Subsequent studies reported the ability of caspase-1 to confer pharmaco-resistance in animal models of epilepsy, though the exact molecular mechanism remains unknown." (PMID 39014496, 2024). "VX765, an inhibitor of caspase-1/-4, is an orally absorbed prodrug of the active metabolite and has been demonstrated to be safe for humans as tested in aphase 2b human clinical trial against epilepsy." (PMID 35639503, 2022). "Given the possible impact of GPR120 on epilepsy via other signaling pathways, we further add the inhibitor of Caspase-1 on the basis of GPR120 knockdown, trying to verify whether inhibiting the activation of NLRP3 can rescue the impact of GPR120 knockdown on epilepsy." (PMID 35624482, 2022). "In the amygdala-ignited rat epilepsy model, knockdown of NLRP1, NLRP3 and Caspase 1 genes by using siRNA technology also reduced epileptic activity." (PMID 40217546, 2025). "Laboratory studies from epilepsy have shown that the levels of inflammasomes (NLRP1, NLRP3, caspase 1, IL-1β, ASC, AIM2, gasdermin D, IL-18, intracellular calcium ion, sTNFr2) were also elevated." (PMID 40217546, 2025). "In a mouse model of pilocarpine-induced epilepsy, four studies consistently show that inflammation is enhanced through NLRP3, caspase 1, ASC, gasdermin D, IL-1β, and IL-18 pathways." (PMID 40217546, 2025). "Meanwhile, seizures can be rescued by using caspase-1 (downstream effector molecules of NLRP3) inhibitors, further proving that GPR120 regulates epilepsy via NLRP3 inflammation." (PMID 35624482, 2022). "Activation of the NLRP3 inflammasome has been detected during epilepsy, and knockdown of NLRP3 or caspase-1 decreased IL-1β and IL-16 levels and provided neuroprotection against SE-associated neuronal damage." (PMID 31097691, 2019). "In the kainic acid epilepsy mouse model, the results of the three studies collectively point to the signaling pathways of NLRP1, NLRP3, absent in melanoma 2 (AIM2), caspase 1, and ASC playing a key role in the activation of inflammation during epilepsy." (PMID 40217546, 2025).
lupus (21 papers, 2011 to 2025). "In a murine lupus model induced by lupus serum, Il-1r-deficient mice and caspase-1-deficient mice demonstrated major improvements in skin inflammation, with decreased expression of MCP-1 and TNF-α, indicating inflammasome pathways contribute to skin inflammation of LN." (PMID 31427885, 2019). "We then focused on GSDMD, which was significantly upregulated together with caspase-1 and caspase-4 (also known as caspase-11 in mice) upregulation in lupus mice." (PMID 36797275, 2023). "Caspase-1 knockout (Casp1−/−) mice demonstrate strong protection against prion-induced autoantibody production and IFN-I responses, indicating that caspase-1 is likely to be necessary for IFN-I-induced lupus." (PMID 35664004, 2022). "Baicalein also inhibited NLRP3 inflammasome activation by decreasing the expression of NLRP3, caspase-1, and IL-1β, the activation of NF-κB by suppressing NF-κB phosphorylation, and the levels of ROS in pristine-induced lupus mice and LPS-stimulated MDSCs." (PMID 33418975, 2021). "In conclusion, we showed that a novel uncharacterized Gm614, highly expressed in GC B cells of lupus-prone mice, protected GC B cells from death and exacerbated autoimmune symptoms by binding with caspase-1 promoter to suppress its activation." (PMID 33193409, 2020). "A recent study revealed that Casp1−/− mice were strongly protected against pristane-induced autoantibody development and type I interferon responses, indicating that caspase-1 is an essential component in lupus development." (PMID 32528469, 2020). "Western blot analysis showed that baicalein decreased mature caspase-1 p20 subunit and IL-1β in kidneys of lupus mice." (PMID 31023362, 2019). "The elevated inflammasomes observed in the kidneys of lupus mice could explain the increased activation of Caspase 1, likely due to the intense inflammatory environment within renal tissue." (PMID 38881675, 2024). "Unexpectedly, myeloid pyroptosis was not increased with elevated and activated GSDMD during LN, represented as the comparable percentages of caspase-1/11+PI+ cells or caspase-1/11+Hoechst+ cells gated on CD11b+ cells in the kidneys of lupus mice and their controls." (PMID 38831451, 2024). "In the later stage of SLE, the expression of NLRP3 inflammasome and caspase-1 could be detected in podocytes in murine lupus models." (PMID 34707607, 2021). "Moreover, the levels of the p202 protein in BMDMs from non lupus-prone (B6) and a lupus-prone strain of mice (the NZB) were inversely correlated with the activation of caspase-1 by the AIM2 inflammasome." (PMID 22046441, 2011). "This study identified increased activation of both Caspase 1 and Caspase 5/11 in the PBMCs of SLE patients and in the kidneys of lupus mice, indicating the coexistence of both pyroptosis pathways in SLE." (PMID 38881675, 2024). "In addition to inflammasomes, the role of caspase-1 was also investigated in lupus." (PMID 31871956, 2019). "EGCG also inhibited NLRP3 inflammasome activation by reducing NLRP3 expression and production of active caspase-1, IL-1β, and IL-18 in NZB/W F1 lupus-prone mice." (PMID 33418975, 2021). "A recent study revealed that Casp1−/− mice are strongly protected against pristane-induced autoantibodies and type I IFN, indicating that caspase-1 is an essential component in lupus development." (PMID 32528469, 2020). "Both caspase-1 and −11 are required for GSDMD activation upon exposure to lupus serum." (PMID 36797275, 2023). "IgG-depleted lupus serum failed to induce increased activation of caspase-1 and −11, along with the cleavage of GSDMD in neutrophils." (PMID 36797275, 2023). "In systemic lupus erythematosus (SLE), FcγR activation downregulates SERPINB1 in neutrophils, leading to spontaneous activation of caspase-1/-11 and GSDMD cleavage." (PMID 39800780, 2025). "However, lupus serum and LPS were found to activate Caspase 11‐dependent but not Caspase 1‐dependent pyroptosis in macrophages." (PMID 38881675, 2024).
lupus (continued). "Mice lacking caspase-1 were protected against lupus-like features in pristane-induced lupus model." (PMID 31871956, 2019).
multiple sclerosis (21 papers, 2011 to 2025). A progressive autoimmune disorder affecting the central nervous system resulting in demyelination. "Ripk2 has been implicated in the caspase-1 pathway of hypoxia and ischemia-induced neuronal cell death, as well as the pathology of neuroinflammatory diseases such as multiple sclerosis." (PMID 35743792, 2022). "ASC deficient mice were also more protected than caspase-1 deficient mice from a mouse model of multiple sclerosis (experimental autoimmune encephalitis or EAE)." (PMID 22216309, 2011). "Evidence has also emerged that IRF-1 may play an important role in cell death involving caspase-1 activation, which has been associated with oligodendrocyte pyroptosis in encephalomyelitis and multiple sclerosis." (PMID 31871426, 2019). "In multiple sclerosis, caspase-1, IL-18, and IL-1β are positively regulated in PBMCs and in mononuclear cells in the CSF during disease development, and caspase-1 expression is upregulated in demyelinating lesions." (PMID 36298702, 2022). "Caspase-1 contains an IRF-1-binding element, and the caspase-1 activity can be directly modulated by IRF-1 in the development of multiple sclerosis and acute lung injury." (PMID 31871426, 2019). "Caspase-1 suppression obliterates inflammasome activation and pyroptosis of glia in multiple sclerosis models." (PMID 31555089, 2019). "Caspase-1-mediated pyroptosis was shown to play a role in the regulation of various diseases, such as multiple sclerosis, retinitis, and neurological disorders." (PMID 31511005, 2019). "Previously, caspase-1 inhibition protects against cerebral demyelination in a mouse model of multiple sclerosis, suggesting that caspase-1 may play a role in the regulation of white matter integrity." (PMID 38630707, 2024). "Moreover, there is evidence that astrocytes can express all the components of the NLRP3 inflammasome (NLRP3, ASC and caspase-1), and produce IL-1β in various central nervous system diseases, such as multiple sclerosis, neuromyelitis optica, and cerebral infarction." (PMID 37921870, 2023). "LPS stimulation upregulates the expression of the inflammasome related genes, NLRP3, Caspase-1, and IL-1β in PBMC from multiple sclerosis compared to healthy controls." (PMID 27795729, 2016).
HIV-1 infection (20 papers, 2014 to 2025). The type species of lentivirus and the etiologic agent of acquired immunodeficiency syndrome (AIDS). "During HIV-1 infection, programmed cell death, including caspase-3-dependent apoptosis and caspase-1-dependent pyroptosis, contributes to CD4+ T cell loss and immunopathogenesis." (PMID 34987521, 2021). "Notably, Caspase-1 and IL-1β are associated with pryoptosis, or inflammation mediated apoptosis; pryoptosis is linked to progression of HIV-1 infection via CD4+ T-cell depletion." (PMID 32117283, 2020). "An investigation into single nucleotide polymorphisms (SNPs) within NLRP1, NLRP3, NLRC4, CARD8, CASP1, and IL1B genes revealed a significant association between two SNPs residing in NLRP3 and IL1B with increased susceptibility to HIV-1 infection." (PMID 38785555, 2024). "We evaluated the effects of the caspase-1 inhibitor VX-765 on HIV-1 infection in humanized NSG mice engrafted with human CD34+ hematopoietic stem cells." (PMID 36800238, 2023). "Similar to our observations with VbP, we found that IL-1β secretion, cell death, and CASP1 activation (as measured by FLICA assay) were significantly reduced in CARD8 KO versus WT THP-1 cells following HIV-1 infection." (PMID 37417868, 2023). "On the contrary, the expression of Caspase-1 increased significantly in the low-level CD4+ T cell counts group after one year of HIV-1 infection." (PMID 36411423, 2022). "High levels of caspase-1 and caspase-3, and low levels of Bcl-2 in platelet-CD4+ T cell aggregates imply the potential role in CD4+ T cell loss during HIV-1 infection." (PMID 34987521, 2021). "In this study, we first reported the dynamics of Caspase-1 and Caspase-3 levels in the peripheral blood within 2 years of HIV-1 infection in two distinct patient groups." (PMID 25806508, 2015). "The results showed that Caspase-1 and Caspase-3 levels in the CD4High group increased rapidly and then decreased within a short time during early HIV-1 infection." (PMID 25806508, 2015). "One year after HIV-1 infection, Caspase-1 and Caspase-3 levels were increased in the CD4Low group but not in the CD4High group." (PMID 25806508, 2015). "The levels of Caspase-1 and Caspase-3 in three of the patients (patients 10, 11 and 12) showed an obvious increase 12 months after HIV-1 infection." (PMID 25806508, 2015). "Caspase-1 and Caspase-3 levels in two of the patients (patient 8 and patient 9) showed an obvious increase 6 months after HIV-1 infection." (PMID 25806508, 2015). "In conclusion, in this study, we analyzed the dynamics of Caspase-1 and Caspase-3 in the peripheral blood of two distinct patient groups within 2 years of HIV-1 infection." (PMID 25806508, 2015). "Caspase-1 and Caspase-3 levels in the CD4High group first underwent a rapid and robust increase and then decreased after a short time during early HIV-1 infection." (PMID 25806508, 2015). "In all seven of the men (patients 1–7) in the CD4High group, Caspase-1 and Caspase-3 levels increased during early HIV-1 infection (within 6 months of infection) compared with before HIV-1 infection and then decreased within two years of HIV-1 infection." (PMID 25806508, 2015). "In contrast, Caspase-1 and Caspase-3 levels in the CD4Low group were obviously increased after 1 year of HIV-1 infection." (PMID 25806508, 2015). "The increased expression of IL-1β, IL-18 and caspase-1 observed herein among brains from HIV-1 infected persons was highly indicative of inflammasome activation during HIV-1 infection, prompting further investigation of this possibility." (PMID 24886384, 2014). "Therefore, further study is needed to explore how the increased MM affects caspase-1 activated pyroptosis of CD4+T cells in HIV-1 infection, and if the excessive fusion has an effect on it." (PMID 38267841, 2024). "Although the exact mechanisms of CD4+ T-cell loss during HIV-1 infection have not been fully elucidated, recent reports suggest that the Caspase-1–mediated pyroptosis provides the main mechanism." (PMID 39902043, 2024).
HIV-1 infection (continued). "Blockade of caspase-1 and polyamine synthesis intermediates reversed the TregDys phenotype showing the direct role of polyamine pathway in altering T cell functions during HIV-1 infection." (PMID 36693889, 2023). "Therefore, the aim of our study was to investigate the effects of the Caspase-1 inhibitor VX-765 in an humanized mouse model of HIV-1 infection as a therapeutic strategy to reduce HIV-1-induced inflammation and reservoirs establishment." (PMID 36800238, 2023). "HIV-1 infection was reported to lead to Caspase-1-mediated pyroptosis in most CD4 T cells." (PMID 38132483, 2023). "While HIV-1 infection has been linked to caspase 1 activation, to our knowledge, no direct role of PR has been demonstrated." (PMID 31242909, 2019). "Therefore, it is possible that a strong immune response and a large number of cytokines led to increased Caspase-1 and Caspase-3 levels during acute HIV-1 infection in the CD4High group." (PMID 25806508, 2015). "We showed in the current work, that targeting inflammasome activation early after HIV-1 infection using the caspase-1 inhibitor VX-765 might represent a potential therapeutic strategy to improve CD4+ T cell homeostasis, and to reduce viral load and immune activation." (PMID 36800238, 2023). "Expression of caspase-1, NLRP3, and IL-1β was increased in lymph nodes and bone marrow between day 1 and 3 after HIV-1 infection (mean fold change (FC) of 2.08, 3.23, and 6.05, p<0.001, respectively)." (PMID 36800238, 2023). "Song found that the expression of Caspase-1 increased rapidly and then decreased within a short period of time in the high CD4+ T cell counts group during the early stage of HIV-1 infection." (PMID 36411423, 2022). "In HIV-1 infection, more than 95% of CD4+T cells die of caspase-1 mediated pyroptosis." (PMID 38267841, 2024). "To show evidences of early inflammasome sensing of HIV-1 in huNSG mice upon HIV-1 infection, we quantified mRNA expression of genes involved in inflammasome activation (NLRP3, NLRP1, NLRC4, AIM2, IFI16, ASC, CASP1, IL1Β, and IL18) in hCD45+ cells from multiple tissues collected at necropsy." (PMID 36800238, 2023). "Because responses to HIV-1 infection were reduced to a similar level in both CARD8 KO cells and CASP1 KO cells, our findings suggest that the inflammasome response to HIV-1 infection in THP-1 cells is primarily dependent on CARD8, but independent of HIV-1 envelope." (PMID 37417868, 2023). "To date, there have been no reports on the dynamics of Caspase-1 and Caspase-3 and their relationship with disease progression in acute HIV-1 infection." (PMID 25806508, 2015). "To date, there have been no reports on Caspase-1 and Caspase-3 dynamics within the first 2 years after HIV-1 infection." (PMID 25806508, 2015). "In all of the five men (patients 8–12) in the CD4Low group, Caspase-1 and Caspase-3 levels did not increase during early HIV-1 infection (within 6 months) compared with before HIV-1 infection." (PMID 25806508, 2015). "HIV-1 infection induced pro-IL-1β in human microglia at 4 hr post-infection with peak IL-1β release at 24 hr, which was accompanied by intracellular ASC translocation and caspase-1 activation." (PMID 24886384, 2014). "HIV-1 infection significantly induced CD4+ T-cell intrinsic Caspase-1 activity, whereas Caspase-1 inhibition, but not Caspase-3 inhibition, significantly blocked CD4+ T cell depletion." (PMID 24495380, 2014). "Caspase-1 and Caspase-3 levels are not noticeably increased during acute HIV-1 infection in the CD4Low group, which may be the result of a weak immune response in the CD4Low group during acute HIV-1 infection." (PMID 25806508, 2015).